STAMBPL1 (STAM binding protein like 1)
Description:
Zinc metalloprotease that specifically cleaves 'Lys-63'-linked polyubiquitin chains. Acts as a positive regulator of the TORC1 signaling pathway by mediating 'Lys-63'-linked deubiquitination of SESN2, thereby inhibiting SESN2-interaction with the GATOR2 complex. Does not cleave 'Lys-48'-linked polyubiquitin chains.
Synonyms: AMSH-LP; KIAA1373; AMSH-FP; FLJ31524; ALMalpha; bA399O19.2
Tractability: Antibody: the Human Protein Atlas places it where antibodies can reach. PROTAC: ubiquitination databases record sites on it; its protein half-life has been measured.
Target class: Enzyme; Hydrolase
Gene: Protein-coding gene on chromosome 10 (88,879,380 to 88,975,153, forward strand). Ensembl gene ENSG00000138134.
Subcellular location (Human Protein Atlas): Plasma membrane
Pathways (Reactome):
Metabolism of proteins: Metalloprotease DUBs
Gene Ontology:
Molecular function: K63-linked deubiquitinase activity; protein binding; metal-dependent deubiquitinase activity; metallopeptidase activity; peptidase activity
Biological process: cellular response to L-leucine; positive regulation of TORC1 signaling; protein deubiquitination; protein K63-linked deubiquitination
Cellular component: membrane; cytosol; endosome
Genetic constraint (gnomAD): Loss-of-function variants: 35 observed, 39.69 expected, observed/expected ratio (o/e) 0.88, 90% interval 0.67 to 1.17. The upper end of that interval is the gene's LOEUF score, 1.17, which puts it in group 5 of 6, group 1 being the genes least tolerant of losing a copy. Missense variants: 421 observed, 448.71 expected, observed/expected ratio (o/e) 0.94, 90% interval 0.87 to 1.02. Synonymous variants: 139 observed, 154.15 expected, observed/expected ratio (o/e) 0.9, 90% interval 0.79 to 1.04.
Homologues: Orthologues: chimpanzee STAMBPL1 (97% identical), macaque STAMBPL1 (96% identical), rabbit STAMBPL1 (96% identical), pig STAMBPL1 (94% identical), guinea pig STAMBPL1 (93% identical), mouse Stambpl1 (91% identical), rat Stambpl1 (89% identical), dog STAMBPL1 (86% identical), tropical clawed frog stambpl1 (78% identical), zebrafish stambpl1 (67% identical), Drosophila melanogaster CG2224 (40% identical). Paralogues in human: STAMBP (55% identical).